BMAL1 (basic helix-loop-helix ARNT like 1)
Diseases named in the same sentence as BMAL1 in open-access papers (continued):
Sharing a sentence is not in itself a finding about the gene and the disease.
Anxiety (24 papers, 2010 to 2026). Intense feelings of nervousness, tension, or panic often arise in response to interpersonal stresses. "On the other hand, hyperactivity is often associated with elevatedanxiety; however, the anxiety level of Bmal1-/- mice did notsignificantly differ from the wild animals judging by the time spent in thecenter of the arena." (PMID 20519775, 2010). "In the Novosibirsk population (Russia, western Siberia), people aged 25–64 years who are carriers of BMAL1 CT+TT alleles and the T allele have a relatively high risk of anxiety, especially among women, whereas the C/C genotype is the most common genotype in the population." (PMID 41440117, 2025). "Interestingly, in nocturnal mice the specific Bmal1 gene deletion in the SCN causes anxiety-like behavior." (PMID 33915800, 2021). "To date, three BMAL1 single nucleotide polymorphisms (SNPs) have been associated with bipolar disorder and related symptoms in patients with this disease: two of them (rs1481892 and rs7107287) are associated with anxiety, and one SNP (rs1481892) is associated with hyperthymia." (PMID 41440117, 2025). "It was shown that in rats subjected to prolonged LED light, scheduled red-light therapy attenuated anxiety-like behavior and regulated Per1 and Bmal1 gene expression in basal ganglia." (PMID 41440117, 2025). "Subsequent assessment of mice in the open field test further emphasized the impact of a conditional knockout of Bmal1 on anxiety-related behaviors, with opposite effects as observed in the EPM test." (PMID 35755440, 2022). "The conditional ablation of Bmal1 or Per2 from striatal MSNs affected anxiety-related behaviors differently." (PMID 35755440, 2022). "In general, relatively little is known about the role of Bmal1 in the control of anxiety-related behaviors." (PMID 35755440, 2022). "From these two studies, we found that Bmal1+/− and Bmal1 KO mice exhibit a number of similar behavioral deficits, including increased USVs at P14, impaired sociability, excessive grooming, increased anxiety-like behaviors, and motor coordination deficits." (PMID 35682995, 2022). "As deletion of Bmal1 resulted in anxiety phenotypes, we examined the production of IL-1β and expression of inflammatory genes in the hippocampus of both WT and Bmal1-/- mice." (PMID 33446652, 2021). "Sleep deprivation significantly increases anxiety levels, impairs cognitive function in mice, reduces BMAL1 and BDNF expression, and enhances oxidative stress in the hippocampus, whereas the injection of human recombinant protein (rhBMAL1) normalizes these deviations." (PMID 41440117, 2025). "Here, we show that with aging, microglial BMAL1 deficiency leads to deficits in non-spatial and spatial learning and memory and increased anxiety." (PMID 36829230, 2023). "Potential mechanisms of Bmal1 in the control of anxiety-related behavior are poorly understood but may include E-box regulated expression of other clock or clock-controlled genes." (PMID 35755440, 2022). "Accordingly, Bmal1+/− mice exhibited aberrant ultrasonic vocalizations during maternal separation, deficits in sociability and social novelty, excessive repetitive behaviors, impairments in motor coordination, as well as increased anxiety-like behavior." (PMID 35682995, 2022). "Because anxiety-like behaviors are mildly affected by the conditional Bmal1 and Per2 knockout in our study, it is tempting to speculate about a contributing or compensatory role of striatal astrocytes with functional circadian clocks on behavioral control." (PMID 35755440, 2022). "Thus, hyperactive Bmal1-/-demonstrated "normal" level of anxiety, while both hyperactive Clock/Clockand hypoactive Cry1,2-/- had decreased level of anxiety." (PMID 20519775, 2010). "Therefore,hyperactivity and deficit of contextual habituation of Bmal1-/- and Clock/Clockcannot be explained by the increase in the level of anxiety in these mice." (PMID 20519775, 2010).
Anxiety (continued). "We next determined whether Bmal1+/− mice displayed anxiety-like behavior by an open field test." (PMID 35682995, 2022). "Altogether, these results suggest that SD may induce anxiety phenotypes through a mechanism involving disruption of the circadian clock and downstream NF-κB mediated transcriptional activity, in particular through dysregulation of Bmal1 and Clock." (PMID 33446652, 2021). "Furthermore, BMAL1-KO primates showed anxiety and depressive-like behaviors." (PMID 33915800, 2021). "Knocking down expression of Bmal1, a core circadian gene, in the SCN was shown to increase depressive- and anxiety-like behavior in mice which indicates that molecular rhythms in the SCN play a key role in regulating psychiatric-related behaviors." (PMID 35126036, 2021). "Because Per1 and Per2 negatively regulate NPAS2/BMAL1 transcription, this further supports a role for NPAS2 in the regulation of anxiety-like behaviors." (PMID 29163035, 2017). "Consistent with this hypothesis, homozygous Bmal1 knockout in VPA‐exposed mice led to aggravated autistic‐like behaviours and anxiety, along with signs of delayed brain maturation compared with VPA mice alone." (PMID 41501308, 2026). "This is in line with the elevated Scop expression observed in the BLA of Bmal1 cKO mice, leading us to hypothesize that changes in SCOP levels in the BLA have direct effects on anxiety-like behaviors." (PMID 27640726, 2016). "Notably, habenular BMAL1-KO did not affect anxiety or depressive behavior, suggesting that the role of BMAL1 in alcohol consumption is independent of the affective state." (PMID 41440117, 2025). "Astrocytic Bmal1 deletion in the NAc did not affect despair or anxiety." (PMID 37441675, 2023). "Importantly, the anxiogenic and anxiolytic effects of Bmal1 and Scop cKO, respectively, did not exceed the range of the circadian variations of anxiety-like behaviors expressed by wild-type mice." (PMID 27640726, 2016). "Bmal1 ablation alone did neither affect depression-like behavior assessed during the baseline tail suspension test (TST) or nosepoke sucrose preference test (SPT) nor influenced general locomotor and anxiety-related behavior measured in the IntelliCage and open-field test (OFT)." (PMID 39179578, 2024).
hepatocellular carcinoma (23 papers, 2009 to 2025). A malignant tumor that arises from hepatocytes. "Notably, this process was observed both in human primary cells (i.e., NHDF—fibroblasts) and cancer-derived cell lines (i.e., HepG2—hepatocellular carcinoma) and is linked to the expression of Bmal1, the master gene of the circadian clockwork." (PMID 39063035, 2024). "It is well documented that in hepatocellular carcinoma, a hypoxic microenvironment leads to changes in the expression of BMAL1, the core clock gene, thereby promoting tumor progression." (PMID 40535800, 2025). "In vitro studies conducted in human hepatoma lines determined that Bmal1 and Clock expression are required for proliferation and that silencing either gene induced apoptosis and cell cycle arrest." (PMID 39272783, 2024). "A recent study utilizing a genetic deletion mouse model has revealed that the deletion of BMAL1 exacerbates a fibrotic phenotype in colorectal, pancreatic and hepatocellular cancers." (PMID 39216004, 2024). "Capsaicin regulates the rhythmic expression of the circadian clock gene Bmal1 in in vitro experiments using human hepatocellular carcinoma cells." (PMID 37299434, 2023). "BMAL1 was also reported to be highly expressed in diethylnitrosamine-induced hepatocellular carcinoma mice model." (PMID 36439870, 2022). "Here, the authors reveal that induction of the alternative isoform in hepatocellular carcinoma inhibits the circadian clock by repressing BMAL1, and the reintroduction of BMAL1 prevents HCC tumor growth." (PMID 30341289, 2018). "However, the biological functions of BMAL1, especially its involvement in aberrant lipid metabolism in hepatocellular carcinoma (HCC), remain elusive." (PMID 36439870, 2022). "Here we investigated metabolic rhythms in HepG2 cells, a human hepatocellular carcinoma–derived cell line, and the link between these rhythms and the circadian clock in control (Bmal1-wildtype) and Bmal1-disrupted (B-D) cells having their molecular clock impaired." (PMID 36183836, 2022). "Likewise, Bmal1 knockdown led to downregulation of Cyp3a11/CYP3A4 in various hepatoma and colon carcinoma cell lines (i.e., Hepa1-6, Hepa-1c1c7, CT26, HepG2, and Caco-2)." (PMID 31633069, 2019). "Furthermore, in hepatocellular carcinoma, BMAL1 was shown to transcriptionally inhibit glycerol-3-phosphate acyltransferase mitochondrial (GPAM) expression in an Enhancer of zeste homolog 2 (EZH2)-dependent manner, suppressing tumor cell growth by interfering with glycolipid metabolic processes." (PMID 41228459, 2025). "miR-494-3p down-regulates the basic helix-loop-helix ARNT-like protein 1 (BMAL1) gene its involvement in aberrant lipid metabolism, thereby enhancing GPAM-mediated lipid biosynthesis in hepatocellular carcinoma (HCC) cells." (PMID 38740866, 2024). "The knockdown of both ARF-BP1 and PAM in hepatoma cells results in a higher amplitude of REV-ERBα protein rhythms and consequently a lower expression and oscillatory amplitude of Bmal1." (PMID 36142478, 2022). "To test the effects of NO or CO on the activities of REV-ERBα and β in vivo we monitored transcription levels of the endogenous Bmal1 and Rev-erb genes in human embryonic kidney (HEK) 293T and hepatocellular carcinoma (HepG2) cells in response to gas." (PMID 19243223, 2009). "Additionally, BMAL1 and CLOCK can impact the cell cycle of hepatocellular carcinoma cells by regulating the expression of Wee1 and P21, thereby contributing to tumor progression." (PMID 38703241, 2024). "In mouse hepatoma cells, the knockdown of Ddb1 or overexpression of the ubiquitination-defective mutant CRY1 K585A enhances CRY1 stability and increases the amplitude of circadian oscillations as measured by a Bmal1-Luc reporter." (PMID 36142478, 2022).
pancreatic cancer (23 papers, 2016 to 2025). "A marked G2/M phase arrest has been noted in BMAL1-overexpressed pancreatic cancer cells, which was linked to a decreased Cyclin B1 expression after Bmal1 overexpression." (PMID 35733785, 2022). "Reduced BMAL1 expression in pancreatic tumors is associated with increased cancer severity and shortened patient survival." (PMID 33302582, 2020). "Most importantly, the p21 induction observed herein, in response to TH301 treatment, seems to occur independently of both CRY2 and BMAL1 modulation, thus indicating the involvement of alternative pathways, successfully operating in pancreatic cancer cell environments of diverse mutational loads." (PMID 39796036, 2024). "The implications of clock disruption were further assessed with a Bmal1 knockout pancreas cancer model, which revealed that an arrhythmic clock caused accelerated cancer growth and worse survival, accompanied by chemoresistance and enrichment of key cancer-related pathways." (PMID 37262074, 2023). "In several cancers, including HCC, pancreatic cancer, and tongue squamous cell carcinoma, low expression of BMAL1 has been associated with poor prognosis, suggesting that BMAL1 functions as a tumor suppressor and that increasing its expression may be a potential anti-cancer strategy." (PMID 40638681, 2025). "Previous studies have identified many polymorphisms affecting multiple clock genes (BMAL1, CLOCK and NPAS2) that are linked to increased risks in prostate, breast, ovarian and pancreatic cancers." (PMID 36978001, 2023). "We then knocked out the core clock gene, Bmal1, in pancreatic cancer cells, which led to faster tumor growth and worse survival in mice and enhanced chemotherapeutic resistance to standard chemotherapy agents used in the treatment of pancreatic cancer." (PMID 37262074, 2023). "BMAL1 expression is significantly lower in patient samples of pancreatic cancer and head and neck squamous cell carcinoma." (PMID 33302582, 2020). "Previous work on pancreatic cancer demonstrated that BMAL1 expression was lower in malignant tissues than in tissue from non-cancerous controls, as we have also found in malignant breast tissue." (PMID 30348208, 2018). "The core circadian clock gene BMAL1 acts as a potential anti-oncogene in pancreatic cancer; the loss of BMAL1 with PER2 accelerates lung tumorigenesis, and BMAL1 inhibits tumorigenesis and further increases the sensitivity of tongue squamous cell carcinoma to paclitaxel." (PMID 32231148, 2020). "In addition, miR-135b directly targets the BMAL1 3’-UTR and asynchrony between miR-135b and BMAL1 expression impairs the local circadian control in pancreatic cancer cells." (PMID 33089205, 2020).
pancreatic cancer (continued). "Taken together, our findings reveal, for the first time, the BMAL1-independent induction of p21 protein in response to TH301, and demonstrate that modulation of the circadian clock components cannot influence p21 upregulation by TH301 in human pancreatic cancer cell environments." (PMID 39796036, 2024).
Sepsis (23 papers, 2017 to 2026). Sepsis is defined as life-threatening organ dysfunction caused by a dysregulated host response to infection. "This appears to be one of the reasons why myeloid-specific Bmal1 KO mice are more susceptible to sepsis induced by intestinal perforation." (PMID 37569682, 2023). "In this animal model, BMAL1 deficiency increased lethality from sepsis; this was mediated by higher levels of lactate-induced PD-1 expression, which was linked to T-cell apoptosis and MOF." (PMID 35880253, 2022). "The loss of the clock gene, BMAL1, showed increased PD-L1 expression in macrophages, which is associated with poorer sepsis survival." (PMID 35356228, 2022). "The immune checkpoint pathway is suppressed when the clock protein BMAL1 is downregulated, causing sepsis." (PMID 35356228, 2022). "To test the idea that BMAL1 loss in macrophages provides systemic protection from pneumonia, we also measured weight loss, a measure of the systemwide impact of sepsis." (PMID 31900362, 2020). "Conversely, opposite time of day effects were reported in sepsis models, where loss of anti-inflammatory activity of BMAL1 worsens outcome 22–24." (PMID 32848194, 2020). "Bmal1 loss-of-function in M1-activated macrophages causes mitochondrial dysfunction, thereby potentiating mROS production and Hif-1α protein stabilization, which probably contributes to the increased sepsis-induced inflammatory damage reported for M-BKO mice." (PMID 32396064, 2020). "It has been reported that deletion of the core clock gene Bmal1 from cells of the Lyz2 lineage causes an expansion of Ly6Chi monocytes, and is associated with increase inflammatory cytokine production and enhanced lethality in a sepsis model." (PMID 29234010, 2017). "Another study demonstrates that the circadian factor BMAL1 regulates innate immunity in sepsis and protects against sepsis-induced ALI by suppressing CXCL2 expression." (PMID 40806591, 2025). "In support, mortality and peritoneal macrophage MiR-155 expression increased further in Bmal1 knockout mice with LPS-induced sepsis." (PMID 39968295, 2025). "The rhythmicity of Bmal1, Per1/2, Cry1, Rev-Erb-α, and Rev-Erb-β in whole-blood is lost in patients with sepsis or septic shock, likely reflecting the changes in immune cells." (PMID 39968295, 2025). "Our prior research revealed that the Bmal1 gene plays a protective role in models of sepsis-induced AKI." (PMID 39858471, 2025). "A similar phenomenon occurs in the hippocampus and microglia of adult Sprague-Dawley male rats for Clock, Bmal1, Per1/2, and Rev-Erb-α in response to lipopolysaccharide (LPS)-induced sepsis." (PMID 39968295, 2025). "Research on the circadian rhythm gene Bmal1 in acute kidney injury (AKI) is comprehensive, addressing various causes including AKI resulting from COVID-19, sepsis, ischemia–reperfusion (IR), and drug exposure." (PMID 39858471, 2025). "It has been further shown that LPS-induced sepsis in C57BL/6 male mice led to higher relative mortality when initiated in the rest phase when Bmal1 is low, compared to initiation during the active phase when Bmal1 is high." (PMID 39968295, 2025). "Circadian clock gene, such as BMAL-1, is also related to many dysfunctions, including immune dysfunctions and sepsis." (PMID 39296207, 2024). "This BMAL1-lactate axis controls T cell survivability in sepsis through production of the immune checkpoint protein PD-L1 by BMDMs." (PMID 37569682, 2023). "Circadian rhythm disruption and dysregulation of CLOCK genes such as Bmal1, are reported in sepsis patients." (PMID 36865524, 2022). "Our data rather demonstrates, that while feeding dependent availability of glucose and glycogen is a prerequisite, optimal protection from sepsis mortality requires the presence of BMAL1 regulated FXR." (PMID 33980856, 2021). "In murine models, genetic ablation of the myeloid Bmal1 gene results in an increased inflammatory response in experimental sepsis." (PMID 33900485, 2021).